USP4 (ubiquitin specific peptidase 4)
Diseases named in the same sentence as USP4 in open-access papers (continued):
Sharing a sentence is not in itself a finding about the gene and the disease.
liver cancer (7 papers, 2020 to 2025). An epithelial or non-epithelial malignant neoplasm that arises from the liver. "In liver cancer, the low expression of microRNA-148a can increase the expression of the downstream molecule USP4, thereby promoting the proliferation and migration of liver cancer cells." (PMID 36969062, 2023). "Suppression of LINC01234 expression was found to restrain liver cancer progression via the mediation of the miR-513a-5p/USP4/TGF-β axis." (PMID 35923244, 2022). "Using quantitative proteomics analysis, cyclophilin A (CypA) was chosen to be another potential target of USP4 in liver cancer which was further confirmed by Co-IP assay." (PMID 32669974, 2020). "In summary, silencing of LINC01234 notably inhibited the tumorigenesis of liver cancer via mediation of miR-513a-5p/USP4/TGF-β1 axis." (PMID 33178601, 2020). "Altogether, LINC01234 knockdown inhibited the tumorigenesis of liver cancer via mediation of miR-513a-5p/USP4 axis." (PMID 33178601, 2020). "USP4 exerted its tumor-promoting role in liver cancer by deubiquitinating and stabilizing TβRI and then activated TβRI/pSmad2 signaling pathway which strengthened cell migration and invasion capacity both in vitro and in vivo." (PMID 32669974, 2020). "Additionally, the expression of USP4 in liver cancer cells was notably upregulated by miR-513a-5p antagomir but inhibited by miR-513a-5p agomir." (PMID 33178601, 2020). "Current study was consistent to this data, suggesting that LINC01234 could modulate the tumorigenesis of liver cancer via mediation of USP4/TGF-β axis." (PMID 33178601, 2020). "Downregulation of LINC01234 could inhibit the tumorigenesis of liver cancer via mediation of miR-513a-5p/USP4/TGF-β axis." (PMID 33178601, 2020). "TGF-β signaling pathway is involved in the modulation of USP4 to liver cancer progression." (PMID 32669974, 2020). "Our result was consistent to this previous study, confirming that LINC01234 could mediate the progression of liver cancer via indirectly targeting USP4." (PMID 33178601, 2020). "It has been previously confirmed that USP4 could act as a tumor promoter in liver cancer." (PMID 33178601, 2020). "In addition, LINC01234 knockdown could inhibit the growth, migration and invasion of liver cancer cells via mediating the miR-513a-5p/USP4 axis." (PMID 33178601, 2020). "Therefore, both lncRNA H19 and USP4 can be used as targets to liver fibrosis treatment which may be the precancerous lesions of liver cancer." (PMID 32669974, 2020). "However, the difference of USP4 level between liver cancer and adjacent normal tissues is not significant." (PMID 33178601, 2020). "Besides, the difference of USP4 expression among different stages of liver cancer is not obvious." (PMID 33178601, 2020).
liver fibrosis (7 papers, 2020 to 2025). "Deubiquitinating TβRI and stimulation of TGF-β signaling pathway also associate USP4 with liver fibrosis and cirrhosis where it facilitates activation of hepatic stellate cell and EMT in hepatocytes." (PMID 33681193, 2021). "A study has shown that H19 exacerbates liver fibrosis by interacting with miR-148a to induce overexpression of USP4, leading to activation of HSCs by inhibiting degradation of Smad4 or TGF-βRI and enhancing TGF-β signaling." (PMID 39195573, 2024). "H19 promotes the transdifferentiation of HSCs into myofibroblasts via the TGF-β1 pathway, while the downregulation of the antifibrotic miR-148a in liver fibrosis inhibits HSCs activation by targeting ubiquitin-specific protease 4 (USP4)." (PMID 39195573, 2024). "Specifically, in liver fibrosis, lower levels of miR-148a and miR-27b lead to the overexpression of USP4 in hepatic stellate cells and hepatocytes." (PMID 33681193, 2021). "Therefore, in the current research, we demonstrate the role of USP4 in autoimmune hepatitis induced fibrosis and examine the function of Vialinin A in prevention of liver fibrosis." (PMID 33295107, 2021). "However, the role of USP4 in liver fibrosis is controversial as previous reported." (PMID 33295107, 2021). "In fibrotic liver tissues, USP4 was released through overexpression of lncRNA H19 sponging miR-148a and stabilized TβRI expression through deubiquitination to activate TGF-β signaling pathway which induced liver fibrosis." (PMID 32669974, 2020). "In addition, liver X receptor-α acts as a protective protein to prevent TGF-β-induced liver fibrosis through enhancing downstream cannabinoid receptor 2 transcription and miR-27b rather than miR-148a expression, thereby hinders USP4 expression and inactivates TGF-β signaling pathway." (PMID 32669974, 2020).
esophageal cancer (5 papers, 2020 to 2023). A primary or metastatic malignant neoplasm involving the esophagus. "High USP4 is associated with a worse outcome in gastric cancer and pancreatic cancer and a better outcome in esophageal cancer." (PMID 37308746, 2023). "In esophageal cancer, higher expression of USP4 was observed in tumor tissues than in para-tumor tissues." (PMID 32669974, 2020).
gastric cancer (5 papers, 2020 to 2025). A primary or metastatic malignant neoplasm involving the stomach. "Because of the limited condition of our animal facilities, we are not able to perform some in vivo experiments to further verify the tumor-promoting role of USP4 in gastric cancer development." (PMID 37624791, 2023). "Overexpression of USP4 promotes cell proliferation, glucose uptake, and lactate production in gastric cancer cells." (PMID 37624791, 2023). "On the other hand, knockdown of USP4 in gastric cancer cells led to a decrease in the expression of GLUT1 and LDHA." (PMID 37624791, 2023). "USP4 affects cell proliferation and enhances the Warburg effect in gastric cancer cells by upregulating PKM2." (PMID 37624791, 2023). "Because USP4 has been shown to regulate PKM2 in gastric cancer cells, we wonder if USP4 will affect the Warburg effect." (PMID 37624791, 2023). "Our current work indicates that USP4 not only promotes proliferation but also enhances the Warburg effect in gastric cancer cells by regulating PKM2." (PMID 37624791, 2023). "USP4 established its tumor-promoting function (enhancing cell proliferation and the Warburg effect) in gastric cancer cells by upregulating PKM2." (PMID 37624791, 2023). "Second, USP4 increased the level of PKM2 in gastric cancer cells." (PMID 37624791, 2023). "Similarly, the colony formation assay results indicated that USP4 promotes gastric cancer proliferation by regulating PKM2." (PMID 37624791, 2023). "USP4 plays a tumor-promoting role in gastric cancer cells by regulating PKM2." (PMID 37624791, 2023). "Nevertheless, the relevant pathogenic roles of USP4 in gastric cancer have not been well investigated and require further exploration." (PMID 37624791, 2023). "However, based on our current data, we infer that USP4 may function as an oncogene in gastric cancer and could be a good candidate for target-directed gastric cancer drug development through further studies." (PMID 37624791, 2023). "Therefore, we examined the glucose uptake and lactate production of gastric cancer cells in the presence or absence of USP4." (PMID 37624791, 2023).
lung fibrosis (4 papers, 2022 to 2025). "In summary, the MIR99AHG/miR-136-5p/USP4/ACE2 signalling axis regulates lung fibrosis and EMT, thus inhibiting LUAD progression." (PMID 36138468, 2022). "Our results suggest that MIR99AHG inhibits pulmonary fibrosis through the miR-136-5p/USP4 pathway." (PMID 36138468, 2022). "Our study suggests that the MIR99AHG/miR-136-5p/USP4/ACE2 signaling axis regulates the process of EMT and lung fibrosis." (PMID 36138468, 2022). "To find the correlation between USP4 and fibrosis, we found that ACE2 plays an important role in the process of lung fibrosis and EMT." (PMID 36138468, 2022). "Therefore, USP4 may contribute to the progression of pulmonary fibrosis, which, however, has not yet been studied." (PMID 36138468, 2022).
rheumatic heart disease (4 papers, 2020 to 2025). An autoinflammatory condition following an infection with Group A Beta Hemolytic Streptococcus (GABHS), in which the heart is attacked by antibodies formed in reaction to a recent GABHS infection. "Increased mRNA levels of USP4 and IL-17, but not of RORγt, were detected in CD4+ T cells from patients with rheumatic heart disease, indicating that USP4 could serve as a therapeutic target in Th17-driven autoimmune disorders." (PMID 41436460, 2025). "For example, USP4 has been shown to interact with and deubiquitinate RORγt, promoting its function and IL-17A transcription in rheumatic heart disease; similarly, USP7 has been found to promote lupus nephritis by regulating NF-κB p65 signaling via JMJD3 stabilization." (PMID 39134949, 2024). "In patients with rheumatic heart disease (RHD), an autoimmune disease, USP4 was found to be significantly elevated in CD4+ T cells." (PMID 33681193, 2021).
cardiac hypertrophy (3 papers, 2020 to 2025). "Overexpressing PPARα and USP4 mitigated the exacerbation of PO‐induced cardiac hypertrophy and dysfunction caused by Lgr6 deficiency." (PMID 40211903, 2025). "Cardiomyocyte‐specific overexpression of USP4 effectively alleviated PO‐induced cardiac hypertrophy and dysfunction in mice with Lgr6 deficiency." (PMID 40211903, 2025). "Overexpression of PPARα and USP4 ameliorated PO‐induced cardiac hypertrophy in Lgr6‐deficient mice." (PMID 40211903, 2025). "LGR6 overexpression ameliorates cardiac hypertrophy by regulating metabolic reprogramming through USP4‐PPARα pathway." (PMID 40211903, 2025). "Besides, the myogenesis suppressive role of USP4 was also found to ameliorate angiotensin II-mediated pathological cardiac hypertrophy both in vitro and in vivo." (PMID 32669974, 2020). "In addition, while this study primarily focuses on the role of the USP4/PPARα signaling pathway in Lgr6‐mediated regulation of pathological cardiac hypertrophy, we acknowledge that other potential mechanisms may exist and warrant further investigation in the future." (PMID 40211903, 2025). "Recently, accumulating evidence have confirmed the function of USP4, USP10, USP18, and USP25 in the regulation of pathological cardiac hypertrophy and remodeling, suggesting a possible involvement of the USP family in pathological cardiac remodeling." (PMID 38481817, 2024). "Additionally, after 8 weeks of TAC, Maresin1 alleviated PO‐induced cardiac hypertrophy and fibrosis, and promoted the deubiquitination and stabilization of PPARα through the PKG/CREB1/USP4 pathway." (PMID 40211903, 2025).
cervical cancer (3 papers, 2020 to 2024). A primary or metastatic malignant neoplasm involving the cervix. "The antiviral effect may make USP4 a potential target for virus-induced cancers, such as cervical cancer." (PMID 32669974, 2020). "However, the detailed effect of USP4 in cervical cancer should be further explored." (PMID 32669974, 2020).
diabetes (3 papers, 2021 to 2024). "Although no direct research on the skin has been reported, USP4 is potentially involved in the inflammatory mechanisms associated with chronic metabolic diseases, such as hepatitis and diabetes." (PMID 39598151, 2024). "Furthermore, Gastrodin has been shown to upregulate the expression of USP4 and enhance the interaction between USP4 and insulin receptors to treat diabetes." (PMID 38322269, 2024). "Although there have not been reports that USP4 is directly associated with diabetes, the high expression of USP4 has an ameliorative effect on other metabolic diseases." (PMID 34603025, 2021).
esophageal squamous cell carcinoma (3 papers, 2023 to 2024). Esophageal squamous cell carcinoma (ESCC) is a type of esophageal carcinoma (EC) that can affect any part of the esophagus, but is usually located in the upper or middle third. "USP4/TAK1 plays a critical role in the progression of esophageal squamous cell carcinoma (ESCC) by regulating proliferation, migration, and invasion." (PMID 39048965, 2024). "Similarly, in esophageal squamous cell carcinoma (ESCC), USP4 exhibits significant upregulation, driving ESCC progression by targeting TAK1." (PMID 39393052, 2024). "Nevertheless, the biological roles and precise mechanism of USP4 in esophageal squamous cell carcinoma (ESCC) progression are not understood." (PMID 37949874, 2023).
multiple myeloma (3 papers, 2021 to 2024). "High expression of OVCA2, PAFAH1B3, USP4 and SIAE, and low expression of PCED1B, are poor prognostic markers in MM, suggesting a role for these esterases in myeloma biology." (PMID 33531688, 2021).
ovarian carcinoma (3 papers, 2020 to 2024). A malignant neoplasm originating from the surface ovarian epithelium. "In addition, we identified several loss-of-function mutations of USP4 from breast and ovarian cancer database." (PMID 38734703, 2024). "Based on the role of USP4 in stabilizing BRCA1, we infer that loss or aberrant expression of USP4 may play a role in non-familiar breast and ovarian cancer and could correlate with the altered BRCA1 level." (PMID 38734703, 2024). "PIK3R3 expression was lower in USP4, SPTBN1, and SORBS2-mutant ovarian cancer patients than in ovarian cancer patients with wild type genes." (PMID 35761259, 2022).
prostate carcinoma (3 papers, 2020 to 2025). A carcinoma that arises from epithelial cells of the prostate gland. "In prostate cancer, METTL3 improves the YTHDF2–HNRNPD-recognized degradation of ubiquitin-specific peptidase 4 (USP4) by mediating m6A modification on A2696 and then maintains the ubiquitin of ELAV-like RNA-binding protein 1 (ELAVL1), giving rise to the migration and invasion of cancer cells." (PMID 35804965, 2022).
autoimmune hepatitis (2 papers, 2021 to 2024). Hepatitis caused by autoantibodies. "Our present study clearly demonstrated that inhibiting USP4 expression alleviates the fibrosis progress in autoimmune hepatitis." (PMID 33295107, 2021). "It clearly indicates that Vialinin A can reduce USP4 level in the liver of autoimmune hepatitis, which contributes to reduction of inflammation and fibrosis in the liver." (PMID 33295107, 2021). "In conclusion, USP4 was significantly elevated in autoimmune hepatitis mice and Vialinin A reduced USP4 level and attenuate inflammation and fibrosis in the liver." (PMID 33295107, 2021). "USP4 shows significant upregulation in autoimmune hepatitis." (PMID 38322269, 2024). "Additionally, it has been reported that CB2 inhibited USP4, leading to the stabilization of TGF-β1R, and subsequently ameliorating hepatic autoimmune hepatitis." (PMID 38322269, 2024). "In this study, the finding that USP4 has a crucial regulatory role in autoimmune hepatitis fibrosis may provide new clues for AIH treatment and Vialinin A may provides a new therapeutic drug for AIH patients." (PMID 33295107, 2021). "However, its role in regulation of USP4 and others is still not clear, especially in autoimmune hepatitis." (PMID 33295107, 2021).
glioma (2 papers, 2022 to 2023). A benign or malignant brain and spinal cord tumor that arises from glial cells (astrocytes, oligodendrocytes, ependymal cells). "Ubiquitin-specific Protease 4(USP4) is the gene with the highest HR in our constructed signature and is associated with poor prognosis in gliomas." (PMID 35774799, 2022). "First, a survival analysis using the GEPIA database revealed that increased USP4 expression in glioma patients was linked to poor outcomes." (PMID 35774799, 2022). "Our cell tests revealed that USP4 was highly expressed in glioma, and that knocking down USP4 expression dramatically reduced the activity, invasion, and migratory ability of glioma cells." (PMID 35774799, 2022). "Our research established a foundation for understanding the role of ubiquitination genes in gliomas and identified USP4 as a possible glioma biomarker." (PMID 35774799, 2022). "Furthermore, examination of individual-cell sequences and transcriptome profiles reveals ubiquitination-related patterns in glioma and discovers USP4 as a new biomarker." (PMID 37781198, 2023). "To begin, qRT-PCR revealed that USP4 expression was up-regulated in all four glioma cell lines when compared to normal control NHAs cell lines, with the highest expression in U87-MG and LN229 cell lines, so gene knockdown was performed in these two cell lines (*P<0.05, **P<0.01)." (PMID 35774799, 2022). "Finally, cell studies were utilized to confirm that USP4, the most important HR gene in the signature, was expressed and functioned in gliomas." (PMID 35774799, 2022). "This adds to the evidence that USP4 has a function in gliomas." (PMID 35774799, 2022). "USP4 was also discovered to be a potential target for gliomas in our research." (PMID 35774799, 2022).
Hepatic steatosis (2 papers, 2020 to 2025). Steatosis is a term used to denote lipid accumulation within hepatocytes. "USP4 deficiency in mice hepatocytes exacerbated hepatic steatosis, insulin resistance and inflammatory response induced by high fat diet." (PMID 32669974, 2020). "This study implies a potential drug role of USP4 in fatty liver therapy." (PMID 32669974, 2020). "Mechanistically, ectopic administration of USP4 directly targeted to deubiquitinate TAK1 and suppressed the activation of NF-κB signaling pathway which ameliorate the extent of fatty liver." (PMID 32669974, 2020).
Insulin resistance (2 papers, 2021 to 2023). Increased resistance towards insulin, that is, diminished effectiveness of insulin in reducing blood glucose levels. "High fat diet–induced insulin resistance was aggravated and reversed by hepatocyte-specific Usp4 deficiency and Usp4 overexpression, respectively, as assessed by fasting insulin levels, homeostasis model assessment-insulin resistance (HOMA-IR), glucose tolerance tests, and insulin tolerance tests." (PMID 36834633, 2023). "Upregulation of USP4 reduces the ubiquitination and degradation of insulin receptors, upregulates the level of insulin receptors, and ultimately improves insulin resistance." (PMID 34603025, 2021). "Likewise, hepatic USP4, 10, and 18 restore insulin resistance, whereas USP14 and 20 decrease it." (PMID 36834633, 2023).
osteosarcoma (2 papers, 2022 to 2024). A usually aggressive malignant bone-forming mesenchymal neoplasm, predominantly affecting adolescents and young adults. "Deubiquitination of PDGFRβ mediated by USP17 and USP4 leads to dysregulated downstream signaling of STAT3 transduction and transcription, impacting osteosarcoma cell proliferation." (PMID 39062505, 2024). "In order to assess the effect of USP4 and USP17 on PDGFRβ stability, we transiently overexpressed USP4 and USP17L22 in U2OS osteosarcoma cells that naturally express PDGFRβ." (PMID 35064336, 2022).
adrenocortical carcinoma (1 paper, 2015). "USP4 had previously been identified as being up-regulated in adrenocortical carcinoma using transcriptional profiling." (PMID 25605410, 2015). "The up-regulation of USP4 and USP38 was identified in adrenocortical carcinoma using microarray gene expression analysis." (PMID 25605410, 2015).
age (1 paper, 2025). A temporal measurement of the time period elapsed since an identifiable point in the life cycle of an organism. "By uncovering the role of EPS8/RAC signaling and its regulation by USP4, we provide insights that may contribute to the development of targeted therapies to prevent or delay distinct age-related neurodegenerative diseases." (PMID 40903652, 2025).
asthma (1 paper, 2025). "The USP4 and hsa‐miR‐136‐5p expressions were also effectively mediated by luteolin and found to be a vital approach in treatment of asthma." (PMID 39830909, 2025).